INS (insulin)
Diseases named in the same sentence as INS in open-access papers (continued):
Sharing a sentence is not in itself a finding about the gene and the disease.
metabolic syndrome (continued). "This parameter is also associated with metabolic syndrome, insulin sensitivity and other age-related functional disorders." (PMID 36937871, 2023). "NAFLD is also associated with dysregulated lipid metabolism and insulin signaling, both of which contribute to development and severity of metabolic syndrome." (PMID 36875069, 2023). "To confirm that changes in insulin sensitivity are associated with dyslipidemia in BAT, we analyzed genes related to FA metabolism in the BAT of WT and GPR84-KO mice." (PMID 37856216, 2023). "The reduction of sCD36 after weight loss was significantly in correspondence with improved insulin sensitivity, dyslipidemia, and liver fat estimated by ultrasonography in obese children." (PMID 40625574, 2023). "Instead, we analyzed the relationship between metabolic syndrome and glucagon to insulin ratio, which are strongly associated with cardiovascular disease in patients with T2DM." (PMID 37762748, 2023). "Dysregulation in ketogenesis is also associated with the pathogenesis of NAFLD and decreased insulin sensitivity, an important manifestation of the metabolic syndrome." (PMID 37512587, 2023). "We investigated the association between glucagon to insulin ratio and metabolic syndrome in patients with T2DM." (PMID 37762748, 2023). "The systemic blockade of VEGF-C/VEGFR-3 causes changes in insulin sensitivity, so it can be a treatment target in metabolic syndrome." (PMID 37692568, 2023). "SNPs in this gene are associated with elevated triglyceride and glucose levels and altered insulin sensitivity, and they have been implicated in several metabolic disorders (e.g., metabolic syndrome and type 2 diabetes mellitus)." (PMID 37761915, 2023). "Although numerous studies have shown profound effects of dietary polyphenol interventions on improving insulin signaling and attenuating dyslipidemia; for decades, mechanisms underlying these beneficial effects remain elusive." (PMID 37160898, 2023). "Another metabolic pathway, glycosphingolipid biosynthesis, has been shown to improve insulin sensitivity, which is a hallmark of metabolic syndrome." (PMID 37855616, 2023). "The use of recombinant IL‐37 for treatment in mice with metabolic syndrome was associated with improved insulin sensitivity and lower levels of pro‐inflammatory cytokines." (PMID 36757903, 2023). "Hypertension and dyslipidemia together with abdominal obesity are components that constitute the metabolic syndrome, sharing underlying mechanisms such as insulin resistance and genetic predisposition." (PMID 38125283, 2023). "In a research of middle-aged Caucasian volunteers, it was discovered that there was a substantial association between poor sleep quality and metabolic syndrome, as well as between sleep condition and insulin, fasting glucose levels, and insulin resistance." (PMID 38050514, 2023). "Obesity has been linked to metabolic syndrome, glucose hypometabolism, and insulin sensitivity or resistance." (PMID 35409283, 2022). "In a cross-sectional study of 1108 Swedish individuals, an independent association between Hcy and serum insulin was closely related to metabolic syndrome." (PMID 35303918, 2022). "Smoking was also found to be associated with metabolic syndrome through its effect on elevating blood pressure, increasing insulin resistance and altering lipid metabolism." (PMID 36408037, 2022). "In patients with metabolic syndrome, treatment with pioglitazone (an antidiabetic drug) reduced high-risk ceramide levels and concomitantly enhanced insulin sensitivity." (PMID 35365690, 2022). "Thyroid hormones (TH) are essential for metabolism regulation and are associated with changes in body weight, energy expenditure, insulin sensitivity, and dyslipidemia." (PMID 36651452, 2022). "The SOCS family proteins are associated with insulin signaling and growth hormone (GH) signaling, which are associated with metabolic syndromes." (PMID 35626153, 2022).
metabolic syndrome (continued). "Lipid metabolism disorders will cause dyslipidemia, β -cell insulin secretion function is damaged, and excessive fatty acids hinder the removal of glucose and eventually lead to T2DM." (PMID 35845591, 2022). "People who are overweight or obese are more likely to develop metabolic syndrome, increase sympathetic excitability, reduce insulin sensitivity, increase the risk of CHD." (PMID 35546659, 2022). "A cross-sectional study of 284 patients found lower serum adiponectin levels were associated with metabolic syndrome status, even when confounding factors (e.g., serum lipid and insulin levels) were controlled." (PMID 35722087, 2022). "The most likely cause of atherogenic dyslipidemia in T2DM is increased hepatic TG synthesis secondary to insulin resistance mediated free fatty acid flux." (PMID 35104300, 2022). "In the SHAPE cohorts, metabolic syndrome and insulin sensitivity were nominally significantly associated with mtDNA-CN, with lower mtDNA-CN associated with metabolic syndrome and lower insulin sensitivity." (PMID 35849594, 2022). "(previously named Eubacterium hallii) was found to be associated with improved insulin-sensitivity in subjects with the metabolic syndrome." (PMID 36544495, 2022). "Vitamin D deficiency increased insulin resistance, decreased insulin production, and was associated with metabolic syndrome." (PMID 35340511, 2022). "Nonalcoholic steatohepatitis (NASH), a leading cause of cirrhosis, strongly associates with the metabolic syndrome, an insulin-resistant proinflammatory state that disrupts energy balance and promotes progressive liver degeneration." (PMID 36535507, 2022). "Numerous studies have demonstrated that metabolic syndrome is associated with skeletal muscle abnormalities, including changes in skeletal muscle fibre composition, metabolism, insulin sensitivity, mitochondrial functions, and strength." (PMID 34939349, 2022). "Hyperandrogenism also causes hirsutism, elevated insulin secretion, glucose intolerance, dyslipidemia, and T2DM." (PMID 36120281, 2022). "Of these secondary outcomes, insulin sensitivity and metabolic syndrome were both associated with mtDNA-CN prior to multiple-testing correction." (PMID 35849594, 2022). "The aim of this study was to assess the combined effects of an obesogenic diet and psychological stress on cardiometabolic risk factors (body weight, dyslipidemia, insulin sensitivity) and postischemic cardiovascular outcomes." (PMID 35076176, 2022). "Thyroid hormones (TH) are essential for development, growth, and metabolism, and thyroid dysfunction is associated with changes in body mass, energy expenditure, insulin sensitivity, and dyslipidemia." (PMID 36651452, 2022). "Our current findings are consistent with findings from previous population-based studies which report that physical activity is associated with a lower risk of metabolic syndrome and improvements in insulin sensitivity and metabolic risk factors." (PMID 36292553, 2022). "Our study found that insulin sensitivity is an essential mediator in the association between fat distribution and dyslipidemia, which is in the agreement with previous findings." (PMID 36387872, 2022). "Causal mediation analysis further suggests that VFM, a key risk factor in metabolic syndrome, fully mediates the associations between hypertension and insulin responses and partially mediates that with postprandial triglyceride response." (PMID 36364763, 2022). "These further allude to the possibility of elevated fasting insulin in isolation initiating the cascade of metabolic syndrome and other possible CVD mechanisms that have been associated with the risk genotype in other studies." (PMID 36313440, 2022). "An early marker of cardiometabolic risk is the metabolic syndrome (MetS), which is a clustering of cardiometabolic traits such as disrupted glucose-insulin homeostasis, adiposity, hypertension, and dyslipidaemia." (PMID 36039146, 2022).
metabolic syndrome (continued). "Metabolic syndromes are associated with deficiency of vitamin D which in turn led to the high resistance of insulin and decreased production of insulin." (PMID 35340511, 2022). "Longitudinal studies have shown that increased breakfast intake improves blood pressure, lipid panels, and glucose and insulin regulation, resulting in a lower risk of dyslipidemia and metabolic syndrome." (PMID 35684120, 2022). "DM is a metabolic syndrome characterized by a loss of capability to oxidize carbohydrates by individuals due to altered insulin production, low insulin production and desensitized insulin receptors." (PMID 35807235, 2022). "Mice knock-out (KO) for Dicer, a ribonuclease involved in miRNA biogenesis, display a form of lipodystrophy reminiscent of the human HALS, including the loss of subcutaneous (SC) fat, insulin resistance, and dyslipidemia." (PMID 35408847, 2022). "We also studied lipid profiles and compared the indices of insulin sensitivity and insulin secretion, since glucose intolerance is associated with dyslipidemia." (PMID 36432554, 2022). "Evidence from human and animal studies show that BVR-A alterations are associated with the aberrant activation of insulin signaling, metabolic syndrome, liver steatosis, and visceral adipose tissue inflammation in obese and diabetic individuals." (PMID 35628384, 2022). "Human studies reported that SPI improve insulin sensitivity (a known risk factor for liver steatosis) in postmenopausal women with abdominal obesity and metabolic syndrome." (PMID 35811988, 2022). "Elevated ferritin levels have also been associated with hypertension, dyslipidemia, elevated fasting insulin and blood glucose levels, central adiposity, and metabolic syndrome." (PMID 36361221, 2022). "The presence of some hallmarks of metabolic syndrome along with the significant reduction in insulin sensitivity indicated IR-O animals were at greater risk of reaching a diabetic state than their lean counterparts." (PMID 35768618, 2022). "The variables that remained significantly associated with myocardial MRGlu were presence of metabolic syndrome (β = −0.625; P = 0.002) and insulin-stimulated glucose disposal (β = 0.463; P = 0.01) explaining 55.9% of its variation." (PMID 35845046, 2022). "When the models were further adjusted for smoking status, physical activity, metabolic syndrome and BMI, the associations with insulin and HOMA-IR remained but the association with glucose was no longer significant." (PMID 34262926, 2021). "There is evidence suggesting that PUFAs omega-3 (n-3) help to improve glucose tolerance, insulin sensitivity and reduce the risk factors for metabolic syndrome." (PMID 34445384, 2021). "The kidney has thus been proposed as an “unwilling accomplice” in the sodium and urate retention associated with the metabolic syndrome, given preserved renal insulin sensitivity in the face of systemic insulin resistance." (PMID 34408667, 2021). "Since metabolic syndrome is also associated with some degree of inflammation, this latter group was divided in two subcategories: moderate and severe insulin dysregulation." (PMID 35011183, 2021). "Other metabolic abnormalities, such as non-alcoholic steatohepatitis, hepatic diseases, polycystic ovarian syndrome, and metabolic syndrome, as well as aging and ethnicity, have also been linked to reduced insulin clearance." (PMID 33668109, 2021). "After further adjustment for smoking status, physical activity and presence of metabolic syndrome, a 10 μg/L increase in selenium was associated with 1.5% (95% CI: 0.4–2.6%) increase in insulin and 1.7% (95% CI: 0.5–2.9%) increase in HOMA-IR." (PMID 34262926, 2021). "In mouse models, AMPK has been associated with improving insulin sensitivity and ameliorating dyslipidemia through its regulation of lipid and glucose metabolism." (PMID 33828528, 2021).
metabolic syndrome (continued). "In this sense, different studies have concluded on the association between NPC1 protein deficiency and metabolic features associated with the impairment of insulin signaling pathways, such as hyperleptinemia and dyslipidemia." (PMID 34579137, 2021). "The role of sexual hormones in modulating lipid metabolism, glucose tolerance and insulin sensitivity is of great interest due to the higher risk of metabolic syndrome development after menopause." (PMID 33926097, 2021). "On the other hand, the asplenic state is related to a high incidence of sepsis, pulmonary embolism, increased peripheral insulin resistance and dyslipidemia, associated with early death." (PMID 34741128, 2021). "So far, it is unclear to what extent carbohydrate reduction achieved by protein-rich, low-glycaemic meal replacement affects the insulin level in overweight or obese people with risk factors for metabolic syndrome." (PMID 33922802, 2021). "Several presumed mechanisms are underlying the pathophysiology of metabolic syndrome, and the most justifiable mechanism is insulin resistance with fatty acid flux." (PMID 35223819, 2021). "Weight loss, increased insulin sensitivity, alterations in gut hormone production and decreases in dyslipidemia and inflammation have all been proposed to contribute." (PMID 33869077, 2021). "In regulating the activity of ovarian and hepatic enzymes involved in androgen production and inducing low-grade inflammation associated with IR, dyslipidemia, and cardiometabolic diseases, insulin’s role is crucial in PCOS." (PMID 33801995, 2021). "In the generalized linear regression analyses, adjusted for age, sex, total energy intake, insulin dose, and physical activity, the continuous nut intake was negatively associated with the metabolic syndrome score, waist circumference, HbA1c, and BMI." (PMID 34836164, 2021). "Inappropriate signaling of insulin has been associated with impaired fat distribution, adipocyte metabolism, and dyslipidemia." (PMID 34001235, 2021). "Lack of PA also results in maladaptive changes to body composition (e.g., increase in body fat), associated with decreased insulin sensitivity, reduced cardiorespiratory fitness and increased dyslipidemia." (PMID 33668262, 2021). "In fact, the mitochondrial metabolic defect causes a wired cellular unbalance, which leads to altered insulin sensitivity, dyslipidemia, and increment of oxidative stress and the consequent DNA damage." (PMID 35050128, 2021). "Numerous clinical studies reveal that myo-inositol supplementation (typically 1–2 g twice daily) can aid insulin sensitivity in metabolic syndrome associated with polycystic ovarian syndrome (PCOS) and in gestational diabetes." (PMID 35052168, 2021). "People who are obese possess increased blood or plasma cholesterol, glucose, and insulin conditions that lead to several other diseases, such as diabetes and other metabolic syndromes, independently associated with unique cognitive deficits." (PMID 35071357, 2021). "Metabolic syndrome represents a multicomponent disorder characterized by abdominal obesity, dyslipidemia, hypertension and impaired insulin sensitivity, which is associated with an increased risk of cardiovascular disease." (PMID 34438804, 2021). "High fibre intake has been linked to improvement of metabolic syndrome by reducing body weight, improving insulin sensitivity and increasing energy expenditure." (PMID 34959755, 2021). "Dietary fiber intake also seems to improve glycemic control and other key risk factors such as abdominal obesity, metabolic syndrome, and insulin sensitivity, all of which are associated with an increased risk of cancer." (PMID 34770068, 2021). "We examined the association between CAV1 and insulin signaling in modifying dyslipidemia and fat composition in overweight and obese women with a prevalent variant in the CAV1 gene." (PMID 34001235, 2021).
metabolic syndrome (continued). "The ESR1 and ESR2 genotypes are associated with insulin sensitivity and metabolic syndrome in Japanese and Chinese women." (PMID 33777160, 2021). "We also found that MT-CN is strongly associated with insulin levels (P = 2.0 × 10−21) and other metabolic syndrome (metS)-related traits." (PMID 34099068, 2021). "In the CAV1 genotype, body fat distribution and dyslipidemia are suggested to be caused via the probable mechanism of disruption in insulin signaling." (PMID 34001235, 2021). "The E4 carriers are strongly associated with lower BMI but increased susceptibility to higher insulin associated metabolic syndromes." (PMID 35071357, 2021). "In a recent review, LIPA was shown to be favourably associated with WC, triglyceride, insulin and the presence of metabolic syndrome after controlling for MVPA." (PMID 32131847, 2020). "Fasting can reverse every major abnormality caused by metabolic syndrome, by increasing insulin and leptin sensitivity, suppressing inflammation and stimulating autophagy." (PMID 32531935, 2020). "It has been well documented that the insulin sensitivity status is correlated with a relatively low visceral fat mass, less adipose tissue dysfunction, and lower risk of dyslipidemia and hypertension." (PMID 32987856, 2020). "In females, chronic psychosocial stress induces changes in the hypothalamus-pituitary-adrenal axis, resulting in increased insulin resistance or adipocyte proliferation, which ultimately causes metabolic syndrome." (PMID 33353082, 2020). "Important examples include the composition of gut microbiota and responsiveness to a Nordic diet, as discussed in a review paper, the relationship of weight loss and insulin and glucose status, or vitamin D responsiveness and markers of metabolic syndrome." (PMID 32516903, 2020). "Direct activation of this isotype improves insulin sensitivity and disorders associated with metabolic syndrome in humans." (PMID 33292260, 2020). "In C57BL/6 male mice, HFD feeding causes a metabolic syndrome that includes increases in body mass, insulin resistance, and systemic inflammation." (PMID 32326950, 2020). "According to one study of non-pregnant French women and men, weight gain over six years was associated with worsening in all metabolic syndrome components especially WC and insulin." (PMID 31936138, 2020). "Only few other studies reported on this topic; they associated higher dose of basal insulin with elements of metabolic syndrome (higher BMI and higher proportion of fat) in T1DM patients." (PMID 32916984, 2020). "Variants assigned to the “insulin action” and “dyslipidemia” clusters corresponded to signals with significantly higher adipose (1.5-fold, p = 0.034) and liver scores (2.9-fold, p = 0.009), respectively." (PMID 33186544, 2020). "Metabolic syndrome represents several cardiovascular risk factors associated with obesity, such as disturbed glucose and insulin homeostasis, atherogenic dyslipidaemia and arterial hypertension." (PMID 32957486, 2020). "Decreased plasma concentration of adiponectin is associated with metabolic syndrome, whereas increased circulatory levels result in the improvement of insulin sensitivity." (PMID 31947953, 2020). "Excessive weight, hyperlipoproteinemia, and decreased insulin sensitivity are traits associated with the metabolic syndrome or MetS." (PMID 32933066, 2020). "In brief, dyslipidemia caused by sucrose consumption is associated with increased risk for hepatic and cardiac disorders, and altered insulin-mediated metabolic responses; features consistent with MS." (PMID 32086249, 2020). "Dietary intake of different marine oils rich in LC-MUFA (in addition to n-3 LC-PUFA) reduces the risk factors of metabolic syndrome in animal models by improving plasma lipid levels and insulin sensitivity." (PMID 32676029, 2020). "As such, a reduction in hepatic insulin sensitivity is associated with the development of the metabolic syndrome." (PMID 32494846, 2020).